INS (insulin)
Diseases named in the same sentence as INS in open-access papers (continued):
Sharing a sentence is not in itself a finding about the gene and the disease.
Hyperinsulinemia (continued). "Since the concentration of IGF-BP1, one of the six IGF binding proteins to which IGF-I is bound, is influenced by insulin, any statement about the role of IGF-I in hyperinsulinism-induced CH is difficult." (PMID 31840185, 2020). "In infants of diabetic mothers and congenital hyperinsulinism, the CHCG is presumably due to the interaction of insulin with the intact insulin receptor." (PMID 31840185, 2020). "Short-term hyperinsulinemia affected mostly the immune cell populations deregulated in FDR subjects, which suggests important interplay between immune system homeostasis and insulin levels." (PMID 30983877, 2019). "In contrast, the CDAHFD regime significantly decreased plasma insulin levels in the C57BL/6J and KK-Ay mice compared with the NCD regime, but it maintained hyperinsulinemia in ob/ob mice." (PMID 31023717, 2019). "One of the proposed mechanisms for its anti-neoplastic effects is the reduction of systemic levels of insulin and insulin-like growth factor-1 (IGF-1), thus lowering the mitogenic activity of hyperinsulinemia." (PMID 31345259, 2019). "In female mice, insulin levels hardly increased upon HFD feeding, whereas males showed pronounced hyperinsulinemia." (PMID 31405127, 2019). "To further examine the effect of HB on hyperinsulinemia, we studied the interaction of FoxO1, PGC-1α, and NF-κB in HEK293T cells using insulin-treated cells." (PMID 30811347, 2019). "Insulin sensitivity is improved by metformin, which increases peripheral glucose uptake and utilization as well as decreases hepatic glucose production and intestinal glucose absorption; while symptoms like sulfonylureas, hyperinsulinemia or weight gain are not caused." (PMID 31323022, 2019). "There was transient hyperinsulinemia in the IGT stage, and the insulin levels were gradually dropped after IGT." (PMID 31737684, 2019). "Nine (69.2%) patients had fasting hyperinsulinemia (serum F-IRI level ≥15 μU/mL)] and 8 (61.5%) were insulin resistant (HOMA-IR score ≥2.5)." (PMID 31500257, 2019). "Next, we assessed miR-101-3p expression by qRT-PCR in the presence of a high concentration of insulin (0.33 μM) for 6 h and/or PAOA (0.25 mM) for 24 h, which mimicked hyperinsulinemia and diet-induced fat accumulation, respectively." (PMID 31671785, 2019). "Therefore, circulating C-peptide levels were measured as a stable surrogate for insulin secretion in male offspring (n = 10/group) to determine whether glucose intolerance in DOSS treatment F1 males resulted from insulin desensitization marked by hyperinsulinemia." (PMID 30728429, 2019). "After a glucose load, both insulin and glucose plasma levels significantly increased in the HFF group, indicating that, even with hyperinsulinemia, the combined administration of fructose and high fat impairs glucose tolerance." (PMID 31689911, 2019). "A crucial role for IR, and compensatory hyperinsulinemia, in the suppression of SHBG levels has been strongly supported by a clear inverse relationship between serum insulin and SHBG levels." (PMID 31402895, 2019). "It is also because this approach would need to take into account the variation of the level of insulin, as during the development of T2DM, compensatory hyperinsulinemia takes place, followed by hypoinsulinemia." (PMID 30445791, 2018). "However, because 20 and 52 week of CANA treatment did not affect serum insulin levels and/or Akt activity in the liver, improvement of hyperinsulinemia does not appear to be a main or direct mechanism to attenuate hepatocellular carcinogenesis in the present study." (PMID 29402900, 2018). "Furthermore, another concept to be highlighted is that hyperinsulinemia, present in insulin-resistant conditions, may favor IR-A/IGF-2 loop activation, thereby potentiating IR-A-dependent mitogenic functions via MAPK/PI3-K/mTOR signaling activation, and worsening the prognosis of TC." (PMID 30513575, 2018).
Hyperinsulinemia (continued). "Indeed, the increase in Homa-IR, as well as the reduction in QUICKI, may just represent an expected consequence of GH-induced basal hyperinsulinemia and very few studies have compared data about the degree of insulin sensitivity in GHD children assessed by different indices." (PMID 29942285, 2018). "Compared with their WT littermates, hyperinsulinemia was evident in both male and female SHROB rats, with circulating levels of insulin being 14.1-fold and 11.5-fold higher, respectively." (PMID 30201044, 2018). "Since both hyperinsulinemia and hepatic steatosis were more pronounced in male SHROB rats, we investigated if insulin signaling pathways were differentially impaired in males and females." (PMID 30201044, 2018). "Interestingly, Y1lox/lox/INS2cre/+ mice also exhibited a significant increase in circulating serum insulin levels in the fed state when compared to control mice, indicating that selective Y1 receptor deletion in islets contributes to the development of hyperinsulinemia." (PMID 30177746, 2018). "Finally, insulin is an upregulator of SCD-16 activity, suggesting that increased SCD-16 associated with increased BMI might reflect an underlying metabolic profile characterized by chronic hyperinsulinemia." (PMID 28465289, 2017). "This lost of sensitivity to insulin in obese animals, as demonstrated by the higher value of HOMA-IR and subsequent hyperinsulinemia, was fully reversed by MET." (PMID 28222147, 2017). "Before stroke, we noted increases in fat mass, serum free fatty acids, insulin, and IGF1 levels in ad libitum‐fed, aged rats that is suggestive of a state of glucose intolerance with hyperinsulinemia." (PMID 28961383, 2017). "Here, using high fat diet (HFD) mice as an experimental model of hyperinsulinemia, we demonstrated that treatment with TUDCA normalizes their plasma insulin concentrations by increasing insulin clearance." (PMID 29093479, 2017). "Additionally, a study with direct infusion of insulin in the rats showed that hyperinsulinemia could mitigate FFA-induced ED in rat aortic rings; however, the direct effect of insulin infusion still remains questionable as the article is in a non-English language with unclear mechanisms." (PMID 28750629, 2017). "Caloric restriction reduces their hyperinsulinemia, and subsequently, hepatic fatty acid synthase level and steatosis, in parallel to inducing hepatic CEACAM1 levels and normalizing hepatic insulin extraction to the level of HCR." (PMID 28396653, 2017). "In our studies, we also showed that chronic HFD-induced hyperinsulinemia was reduced by a single STZ injection and this led to a reduction of insulin levels." (PMID 28798347, 2017). "In conclusion, hyperinsulinemia and hyperdislipidemia at the beginning of the third trimester disturbed placental weight and thickness in the GDM, activating placental insulin mediators." (PMID 28587267, 2017). "A tyrosine kinase inhibitor specific to the insulin and IGF-1 receptors aggravated hyperinsulinemia but prevented insulin signaling and cancer growth." (PMID 28060743, 2017). "Based on the FINS data, hyperinsulinemia was significantly decreased after one month of treatment with HMS5552, indicating an increase in the insulin-sensitizing activity of HMS5552." (PMID 28191470, 2017). "Furthermore, we could not determine whether using insulin as a therapy for T2DM is an important factor because CRA risk might be altered by hyperinsulinemia, thought to be an important promoter of carcinogenesis." (PMID 27535548, 2016). "In the present study, we evaluated the differences in IR levels among subjects with NGT, hyperinsulinemia with normal blood glucose tolerance (HINS), IGT, and newly diagnosed T2DM and analyzed the relatively dangerous factors of insulin sensitivity." (PMID 26770991, 2016). "The compensatory hyperinsulinemia was mainly affecting the later OGTT period, whereby total insulin release was particularly increased in the PCO-NIH subgroup." (PMID 27505055, 2016).
Hyperinsulinemia (continued). "The ob/ob and db/db mice fed the CD for 1 week exhibited hyperinsulinemia, whereas only HFD-fed ob/ob mice showed increased insulin levels." (PMID 26839577, 2016). "Experimental hyperinsulinemia impaired FID (% of dilation at ∆60 pressure gradient) in LHCs (basal: 74.2 ± 2.0; insulin: 57.2 ± 3.3, P = 0.003) and T2DM (basal: 62.1 ± 3.6; insulin: 48.9 ± 3.6, P = 0.01)." (PMID 27796268, 2016). "In general, the serum insulin concentration in HFD-fed C57BL/6J mice was higher than in STD-fed mice due to reduced insulin sensitivity and compensatory hyperinsulinemia." (PMID 27189109, 2016). "Higher glycemia, despite hyperinsulinemia at postnatal day PND21 in pHF Wistar pups, also argues in favor of a decreased insulin sensitivity in this group." (PMID 27618559, 2016). "To test the potential downstream effects of hyperinsulinemia‐induced increased ET‐1 protein expression, we measured the protein expression of ETAR and ETBR receptors in LHCs and T2DM subjects at basal and insulin‐stimulated conditions." (PMID 27796268, 2016). "There was no detectable difference in Akt phosphorylation between genotypes in control (PBS-injected) mice despite baseline hyperinsulinemia of GRIP1 cKO, and insulin-injected WT mice displayed a significantly higher level of pAkt in eWAT and muscle." (PMID 27464507, 2016). "Weight gain was diminished and insulin sensitivity was improved in 3 models (BKS-db/db, NcZ10, TH), and hyperinsulinemia was reduced in 2 models (TH, KK-Ay)." (PMID 27922820, 2016). "In vivo studies observing UCP2 KO mice have shown that these mice develop hyperinsulinism, which suggests that UCP2 is involved in the regulation of insulin secretion." (PMID 27065949, 2016). "OB presented hyperinsulinemia and decreased glucose disappearance constant (38% vs CTL, P <0.05) in IVITT, depicting the whole body insulin-resistant condition." (PMID 25834641, 2015). "Since hyperinsulinemia plays a pivotal role in the progression of NASH, serum insulin was measured in our animal model." (PMID 25826083, 2015). "In this study, we observed the hyperinsulinemia in diabetic CHB patients, suggesting the body responded by increasing serum insulin concentrations to compensate IR." (PMID 25887997, 2015). "Due to this last evidence, in a condition of hyperinsulinemia, IGF1R can be activated both directly by the high circulating levels of insulin and, indirectly, through insulin-mediated upregulation of IGF-1." (PMID 26171112, 2015). "PYY reinforces the insulin action on glucose disposal in muscle and adipose tissue and GLP-1 increases peripheral glucose-mediated glucose uptake independently of hyperinsulinemia." (PMID 26292284, 2015). "Fulghesuet al study showed NAC can have effect on levels of circulated insulin and insulin sensitivity in PCOS women with hyperinsulinemia." (PMID 25653669, 2015). "Hyperinsulinemia is known to increase mTOR/p70 S6K pathway and increased IRS-1/2 serine phosphorylation indicating insulin resistance state of a tissue." (PMID 24460834, 2014). "Whether the impairment in peripheral insulin sensitivity is mainly located in muscle and mostly due to higher disposable free fatty acids, GH is also able to reduce hepatic insulin sensitivity in healthy humans and to counterbalance the anti-lipolytic actions of hyperinsulinemia." (PMID 24498035, 2014). "In liver, hyperinsulinemia is known to suppress the expression of IRS2, thereby attenuating the insulin signaling in liver." (PMID 24982885, 2014). "Several animal models for hyperinsulinemia have been developed by overexpressing InR or IGFR in some tissues, by the short-time administration of insulin, or by feeding animals a high-sugar diet." (PMID 24795642, 2014). "Although these models have contributed to elucidating the molecular mechanisms that regulate insulin/IGF signaling, how hyperinsulinemia affects animal physiology has remained elusive." (PMID 24795642, 2014).
Hyperinsulinemia (continued). "Hyperinsulinemia amplifies bioavailablity of insulin like growth factor-1 (IGF-1), which together with insulin are known to promote human breast cancer." (PMID 24911052, 2014). "Our results show that the serum insulin levels were increased in the MS group when compared to the C group, but the group MS Ovx showed the highest values; therefore, it appears that estrogen may have protective effect against the development of hyperinsulinemia." (PMID 24987414, 2014). "We will first focus on the role of I.R./hyperinsulinemia, the key metabolic alteration in MetS, and then discuss the role of adipokines in the activation of SNS and their interplay with insulin." (PMID 24288531, 2013). "In the clinical setting, while some prospective studies demonstrate that there may be an association between hyperinsulinemia and PCa risk, there are also several studies that do not support a role for insulin in PCa risk and thus it continues to be an area of investigation." (PMID 24058525, 2013). "Therefore, although the main purpose of the clamp technique is usually that of maintaining euglycemia in spite of hyperinsulinemia for measurements of insulin sensitivity, the glucose clamp technique may be used for a variety of other scientific purposes with only slight modifications." (PMID 23762879, 2013). "In contrast, insulin has been shown to enhance GLP-1 secretion in an ERK-dependent manner, and this response of GLP-1 to insulin was attenuated by chronic hyperinsulinemia in human NCI-H716L cells and mouse models in vitro and in vivo." (PMID 23844037, 2013). "Further, hyperinsulinemia is known to reduce the circulating amount of HMV adiponectin independent of clearance, which corresponds to the idea that impaired insulin-signaling is a major determinant of adiponectin level." (PMID 24065958, 2013). "Although insulin is one of the NHE activators, diabetic condition (namely, hyperinsulinemia) as indicated by increased HbA1c, rather reduces ΔK." (PMID 23289667, 2013). "In hyperinsulinemia, the growth hormone receptor (GHR) is upregulated by the increase of insulin concentrations in portal circulation thus increasing GHR signalling and hepatic IGF-I synthesis." (PMID 24073332, 2013). "Hyperinsulinemia has been proposed to promote liver steatosis and hyperinsulinemic patients with NASH treated with insulin-sensitizing agents show improvements of liver steatosis." (PMID 23056165, 2012). "Ultimately, the sums of all of these processes appear to be mediated via an imbalance of insulin substrates, where hypoinsulinemia is characterized by excessive IRS-2 signaling, and hyperinsulinemia with predominant IRS-1 signaling." (PMID 22745692, 2012). "Hence, hyperinsulinemia in gestational diabetes might increase insulin signaling in osteoblasts resulting in increased bone resorption and activation of osteocalcin, which in turn, might be able to improve insulin secretion." (PMID 22844418, 2012). "Thus, SERT deficiency does not attenuate insulin secretion, but it causes hyperinsulinemia." (PMID 22412882, 2012). "The conditions of hyperinsulinism and hyperandrogenism present in PCOS-IR patients modulate the expression and/or phosphorylation of the proteins involved in the insulin pathway at the endometrial level." (PMID 22390153, 2012). "This is the first study to examine the association between genetic variation of the ELOVL6 gene and insulin sensitivity in humans, measured by HOMA as well as hyperinsulinemia at 120 minutes after the OGTT." (PMID 21701577, 2011). "In the basal state, intake of the HFC diet exacerbated the hyperinsulinemia induced by HF consumption, whereas animals fed HFR and control diets had similar plasma insulin levels." (PMID 20064776, 2010). "Nevertheless, MS is distinguished by resistance to hyperinsulinism and insulin, while NIDDM is characterized by the impaired pancreatic beta-cell function and insulin resistance." (PMID 22649614, 2009).
Hyperinsulinemia (continued). "In sharp contrast, parenteral exogenous insulin does not undergo this liver entrapment, a fact that results in peripheral hyperinsulinemia." (PMID 40427546, 2025). "Furthermore, diabetic mice with intact FATP2 develop reduced plasma insulin levels, whereas diabetic mice with FATP2 deletion demonstrate islet hypertrophy and sustained hyperinsulinemia." (PMID 40956612, 2025). "The results indicated that MYO may lower fasting serum insulin (FINS) levels through the insulin-related metabolic pathway, thereby improving IR-related hyperinsulinemia." (PMID 40008316, 2025). "The differences in glucose in mares presented with Cushing’s syndrome with hyperinsulinemia or low insulin are not significant, but were lower (p < 0.001) than the controls showing low or hyperinsulinemia." (PMID 40901060, 2025). "In a placebo-controlled double-blind cross-over study, short-term administration of dapagliflozin (10 mg for 3 days) did not improve whole-body sensitivity of glucose disposal to insulin during euglycemic-hyperinsulinemia." (PMID 39998445, 2025). "In this context, several studies evaluated the effect of insulin on adrenal androgen secretion in PCOS, but results remained conflicting in both cross-sectional and experimental studies of short-term induced hyperinsulinemia." (PMID 40944006, 2025). "Since hyperinsulinemia is known to promote vasodilation and CGRP-mediated neuroinflammatory responses, restoring insulin sensitivity may normalize vascular reactivity and reduce migraine frequency." (PMID 40426647, 2025). "On the other hand, elevated insulin in the fasted state can arise from inability to regulate basal secretion, resulting in sustained hyperinsulinemia without glucose stimulation." (PMID 40013621, 2025). "LY294002, but not PD 0325901, blocked insulin-mediated repression of Igf1r and Irs2, further demonstrating that hyperinsulinemia reduces Igf1r through PI3K signaling." (PMID 40105689, 2025). "In people with T1D, even a single night of partial sleep restriction reduced the sensitivity of whole-body glucose disposal but not EGP to insulin by 18% during euglycemic–hyperinsulinemia." (PMID 39998445, 2025). "In addition, PKCι/λ downstream of insulin signaling is hyperactive and increases BACE1-cleavage of APP and Aβ production in hyperinsulinemia." (PMID 40551140, 2025). "Hyperinsulinemia may additionally be an early change for daughters of women with PCOS, whose insulin levels can be significantly elevated by late puberty compared to pubertal stage-matched controls." (PMID 40013621, 2025). "There were differences in insulin concentration among LDF and HFD groups that may reflect compensatory hyperinsulinemia in response to a continued HFD stress." (PMID 40564946, 2025). "Persistent hyperinsulinemia in the IR state is a potent physiological activator of the PI3K/Akt pathway and can directly antagonize the efficacy of upstream PI3K or Akt inhibitors through an “insulin feedback” effect." (PMID 41208895, 2025). "This reduced clearance is accompanied by compensatory hyperinsulinemia, not hypoinsulinemia, suggesting that the primary defect is in peripheral tissue response to insulin and glucose, not in the pancreatic beta cell." (PMID 40055326, 2025). "In the insulin-resistant liver, hyperinsulinemia fails to suppress VLDL production, while elevated free fatty acid flux from insulin-resistant adipose tissue enhances hepatic triglyceride (TG) synthesis." (PMID 41346943, 2025). "We hypothesized that lowering iatrogenic peripheral hyperinsulinemia via a one-week, reduced-carbohydrate diet (RCD) would improve insulin sensitivity and endothelial function compared with an isocaloric standard carbohydrate diet (SCD)." (PMID 40045281, 2025).